KLF4 (KLF transcription factor 4)
Diseases named in the same sentence as KLF4 in open-access papers (continued):
Sharing a sentence is not in itself a finding about the gene and the disease.
tumor (continued). "KLF4 expression also displayed significant negative correlations with tumor purity in LUAD (r = −0.168, p = 1.70 × 10−4), and nonsignificant positive correlations with tumor purity in LUSC (r = 0.062, p = 1.74 × 10−1), respectively." (PMID 34440860, 2021). "This interface area was also investigated using immunofluorescence by increased magnification, and several cells with combined reaction of KLF4, cytokeratin and vimentin were detected, which might be considered as EMT tumor cells." (PMID 33802627, 2021). "Although for genes like Il15 we did not observe any difference between healthy and tumor-bearing mice in Ficoll or Parsortix samples; others, such as Egr1, Zc3h12a, Klf4, or Nfat5, allowed distinguishing for cancer or CTC presence." (PMID 35153760, 2021). "Furthermore, consistent with our in vitro studies, when we stained tumor sections from the mice injected with EpCAM−/CD133− cells overexpressing KLF4, these tumor sections had increased levels of both the KLF4 and EpCAM proteins." (PMID 32408542, 2020). "In this experiment, Dox was administered simultaneously with chemotherapy, which was administered at a dose intended to stop tumor progression but not reduce the tumor size to facilitate the identification of KLF4-induced phenotypes." (PMID 32944247, 2020). "In order to verify the association of MCT1 expression and stemness properties in human PDAC tissue, consecutive sections of FFPE tumor tissues from PDAC patients (all with resectable T3N1M0 tumors) were immunostained with antibodies directed against MCT1, KLF4, and Sox2, respectively." (PMID 32138176, 2020). "A consideration of the local distribution of associated markers revealed a significant downregulation of the lactate transporter MCT1 at the edge of the tumor, whereas the gene expression of the EMT marker β-catenin and the stemness markers KLF4 and OCT4 was induced at the edge of the tumor." (PMID 32872409, 2020). "In addition, besides KLF4, FBXO32 can target some other unidentified substrates that are important in EMT, cell migration/invasion, and tumor development to establish its dual functions." (PMID 33240028, 2020). "Importantly, in parallel to changes in DNA and histone H3 methylation status, we found a marked re-expression of methylation-regulated tumor suppressor genes: CDK2NB, KLF4, ID4, and TXNIP." (PMID 32138178, 2020). "However, the correlation of KLF4 mRNA levels with the mRNA levels of VEGFA, SLC2A3 and HK2 was only moderate to weak in the analyzed tumor samples (R = 0.5044; R = 0.3348; R = 0.4416)." (PMID 32245394, 2020). "Our results identify KLF4 as one of the transcription factors that can modulate the de-differentiation of tumor cells and regulate the shift between non-CSC and CSC states in HuH7 cells." (PMID 32408542, 2020). "Not surprisingly, there are conflicting reports regarding KLF4 expression in HCC and its association with tumor recurrence and overall survival in HCC patients." (PMID 32408542, 2020). "It thus appears that MRD cells are especially sensitive to KLF4 expression, suggesting that any regimen that induces KLF4 expression in MRD might be especially effective for tumor consolidation therapy." (PMID 32944247, 2020). "Our analysis showed that there is a significant negative correlation between expression of KLF4 and claudin-1 and N-cadherin between the normal-appearing mucosa and tumor tissues (P < 0.001)." (PMID 32566755, 2019). "Expression patterns of p65 and KLF4 might be useful to predict the drug resistance against PS1145 and probably other anti-tumor agents in NPC patients." (PMID 31427673, 2019). "Similarly, genes such as CAV1, ACACB, NTRK2, KLF4, and MYH11 were the key down-regulated hub genes suggesting a possible role of their decreased expression in breast carcinogenesis." (PMID 31292488, 2019).
tumor (continued). "Surprisingly, as the passage of the tumor-derived cells (TDCs) increased, the expressions of stem cell markers such as Oct4, CD133, and Sox2 decreased rapidly while the expression levels of oncogenes including c-Myc, Klf4 and ABCG2 were maintained." (PMID 31727938, 2019). "KLF4, a gut-enriched GKLF and zinc-finger transcription factor, regulates a multitude of processes in cell growth and development, proliferation and differentiation, inflammation, and apoptosis, and is even both a tumor suppressor and oncogene." (PMID 31687083, 2019). "Similarly, in tumor tissues from AOM/DSS-treated mice, KLF4 levels were negatively correlated with mesenchymal markers including SNAI2, β-catenin, and vimentin and positively correlated with the epithelial marker E-cadherin." (PMID 32566755, 2019). "We performed tumor sphere formation assays using Caco-2 and HCT116 cells to enrich cells with CSC-like characteristics, and qPCR showed that expression of the stem cell markers SOX2, OCT4, Nanog and KLF4 was high in the tumor spheres." (PMID 31754405, 2019). "In additional mice sacrificed on days 24–29 for tumor myeloid or T cell analyses, the tumor volumes were also significantly lower in the absence of myeloid Klf4." (PMID 29324844, 2018). "In addition, tumor-infiltrating CD8 T cell numbers were markedly increased and CD8 T cell depletion obviated the slower tumor growth seen in Klf4(f/f);Lys-Cre hosts." (PMID 29324844, 2018). "Initial growth was uniformly slower in the absence of myeloid Klf4, with mean tumor volumes on day 29, with 6.4-fold lower mean tumor volumes in the Klf4(f/f);Lys-Cre recipients." (PMID 29324844, 2018). "Similarly, si-hVDAC1 treatment of A549-derived tumours greatly decreased the expression of ABCG2, SOX2, CD44, CD144, CD133, KLF4, Oct3/4, EPCAM and Nanog, also as evaluated by IHC, immunoblotting or q-RT-PCR." (PMID 30544833, 2018). "Amongst tumor myeloid cells, TAMs predominated over monocytes and granulocytes in this model, and F4/80+ TAMs were increased 2-fold in the absence of Klf4." (PMID 29324844, 2018). "The majority of tumor myeloid cells were F4/80hiLy6Clo/mid TAMs, and these increased approximately 1.5-fold in the absence of myeloid Klf4 (left)." (PMID 29324844, 2018). "All samples showed KLF4-positive staining in the tumor and KLF4-negative staining in adjacent normal tissue." (PMID 28380435, 2017). "Our data support a model in which KLF4 is activated in GSC downstream of the MAPK pathway in part through EGR1, and we further demonstrate that EGR1 acts as a transcriptional regulator of KLF4 in GSCs in-vitro, and its expression level positively correlates with KLF4 in clinical GBM tumor samples." (PMID 28256619, 2017). "RT-PCR and densitometric quantification analysis was used to quantify mRNA expression of a panel of stemness genes (NANOG, OCT-4, SOX-2, KLF4 and C-MYC), in addition to the CSC-specific markers, CD133 and ALDH1, in a cohort of matched normal and tumor lung tissues from NSCLC patients (n=20)." (PMID 29069808, 2017). "What is striking is the fact that, when considering all tumor samples together without separation in groups, we find a highly significant correlation of KLF4 and IGF2 expression (p < 0.0001, Spearman’s rank correlation coefficient r = 0.668)." (PMID 29017567, 2017). "Tumor cells and iHepL cells do not contain transgenes for Oct4 or Sox2, pointing at Klf4 and Myc as probably responsible for induced tumorigenicity and excluding rare partially pluripotent cells as responsible for tumor formation." (PMID 27460218, 2016). "KLF4 deletion by Lgr5-Cre and Rosa-Cre induced precancerous changes but did not induce tumor formation within 2 weeks of KLF4 deletion." (PMID 27277677, 2016). "As a tumor suppressor gene, KLF4 was downregulated in cancer tissues compared with noncancerous tissues in gastrointestinal track." (PMID 27531889, 2016). "And the expression of KLF4, a tumor suppressor, could inhibit SPARC expression to restrain the tumor invasion." (PMID 26731428, 2016).
tumor (continued). "In our study, KLF4 and IRF8 were up-regulated TFs, and IRF8 was a tumor suppressor gene." (PMID 27405725, 2016). "Moreover, the levels of KLF4 are reduced and the levels of VDR are increased in HCC cell lines and primary tumor samples." (PMID 27102441, 2016). "Although much is known about KLF4, the exact molecular mechanisms by which KLF4 works as a transcriptional activator, repressor, tumor suppressor, and oncogene, is not fully elucidated." (PMID 26517087, 2015). "Consistent with its role as a tumor suppressor, KLF4 inhibits cell cycle progression in some, but not all, cell types." (PMID 26431332, 2015). "Taken these observations together, CD44-singaling networks-KLF4-p21-Cyclin D1 could explain, at least in part, the molecular events behind the involvement of CD44 in maintenance of tumor initiating cells." (PMID 25605020, 2015). "Given its role as a tumor suppressor, KLF4 protein levels are decreased in tumors derived from epithelial cells, however the molecular mechanisms involved in KLF4 downregulation in oncogenic epithelial cells, has not been explored." (PMID 25181544, 2014). "In addition to RORC, Krüppel-like factor 4 (KLF4), a transcription factor of cell differentiation, tumor suppression, stem cell properties, and malignant transformation, is another positive regulator of Th17 differentiation." (PMID 24288551, 2013). "We evaluated the expression of the pluri potent stem cell genes Oct4, Sox2 and Klf4, as well as that of the c-Myc, Nanog and Lin28 genes in HCC samples and corresponding adjacent non-tumor liver samples obtained from 57 patients using quantitative real-time reverse transcription-PCR (qRT-PCR)." (PMID 23599755, 2013). "KLF4 was expressed with “++” or “+++” in the 41 normal tissue samples but with “+” or negative in 25 of 41 tumor samples." (PMID 23861801, 2013). "Given that Klf4 and Klf5 have context dependent roles, it is not surprising that Klf4 and Klf5 possess both tumor suppressor and oncogenic functions." (PMID 20514221, 2009). "The complexity does not end here since Klf4 can function either as an oncogene or tumor suppressor in the same tumor type." (PMID 20514221, 2009). "Conversely, when KLF4 functions as a tumor‐suppressive factor within the TME, as exemplified in lung adenocarcinoma, it downregulates NF‐κB2 and CXCR2, concomitantly restrains tumor cell invasion, and enhances the infiltration of CD4+ and CD8+ T cells, macrophages, and other immune subsets." (PMID 41532367, 2026). "In contrast, genes including KLF4 and ZFP36 exhibited differential expression dynamics by group that were not consistently echoed by their group-specific expression levels, thus undermining their prognostic value and instead being relevant predictors of the tumor biology." (PMID 40770193, 2025). "Given the role of KLF4 as a negative cell cycle regulator, persistent KLF4 expression could contrast the tumor growth." (PMID 41463190, 2025). "Furthermore, when examining correlations between tumor KLF4 expression and immune checkpoint genes as a means to predict immunotherapy applications, a negative correlation between KLF4 and a wide range of immunomodulators was noted." (PMID 40299916, 2025). "In situ sequencing also confirmed a consistent pattern: in EpCAMhigh tumor cell-dominated spots, compared to EpCAM-negative cell-dominated spots, there was a more frequent expression of the CD133/PROM1 gene along with the transcription factor genes OCT4/POU5F1, KLF4, and MYC." (PMID 39456890, 2024).
tumor (continued). "Subsequently, using a subcutaneous xenograft mouse tumour model established by injecting SCC9 cells divided into NC, shEphA2, shEphA2 + OE-YAP, and shEphA2 + OE-KLF4 groups, we found that EphA2 knockdown reduced the tumour volume and weight, while YAP or KLF4 overexpression reversed these effects." (PMID 38916835, 2024). "We speculated that tumor cells in those tumor tissues might regulated the tumor stemness through other transcription factors rather than KLF4." (PMID 37809806, 2023). "Tumor spheres originate from self-renewing cells and exhibit an augmented CSC phenotype along with an elevated expression of stemness transcription factors (Nanog, Oct4, KLF4, Lin28, and Sox2), in contrast to their corresponding monolayer adherent cell counterparts." (PMID 37759448, 2023). "To assess whether the upregulation of stem cell transcription factors participate in integrin αvβ3/PI3K/AKT-induced tumor cell proliferation, we measured the gene expression levels of SOX2, Oct3/4, c-Myc, Tert, KLF4 and Nanog in PBS- or FN-treated A549 and Lewis cells by real-time PCR." (PMID 37809806, 2023). "Despite KLF4 being an early-stage ESC and a TF that aids in the maintenance of the embryonic stage in cancer cells, the expression of KLF4 in TNBCs may act as a gene that suppresses tumor growth by targeting CSCs." (PMID 37250812, 2023). "However, we did not observe a significant relationship of KLF4 hypermethylation with tumor location, patient age or histology of the tumor." (PMID 34854470, 2022). "Notably, DHCT treatment of HCC cells resulted in the reduced expression of α7nAChR, JAK2, and cancer stemness markers (CD133, KLF4, and SOX2) as well as decreased ALDH1 activity, thereby suppressing the colony-forming and tumor sphere generation abilities of HCC cells." (PMID 35111269, 2022). "However, combined knockdown of DUB3 and KLF4 did not further promote tumor growth compared with knockdown of DUB3 or KLF4 alone." (PMID 35383144, 2022). "We found that in addition to KLF4 and BMI1, miR-135a also inhibited the expression of MMP2 and MMP9, as shown by Western blot, and inhibited MMP activation, as shown by the decrease in the intensity of MMPSense in FMT, which plays important roles in promoting tumor invasion and metastasis." (PMID 33828977, 2021). "Collectively, these results relate KLF4 to non-Warburg metabolic behaviors that support its role as a tumor suppressor and could make KLF4 a target for new cancer treatments." (PMID 33917010, 2021). "CircPLEKHM3 was found to function as a tumor suppressor in OC by sponging miR-9 to regulate the endogenous expression of breast cancer 1 (BRCA1), DNA heat shock protein family (Hsp40) member B6 (DNAJB6) and kruppel like factor 4 (KLF4) which consequently inactivates oncogenic AKT1 signaling." (PMID 33614648, 2021). "Thus, we speculated that EIF5A2 might promote the tumor initiation and cancer stemness of EOC cells by activating KLF4 expression." (PMID 33726845, 2021). "Compared to 2D monolayers, there was a twofold increase in the expression of the stemness-related transcription factors SOX2 and KLF4 in PA-ECM cultures and a much higher proportion of CD133 + /CXCR4 + cells than in spheres or organoids, which falls in the range of matched PDX tumours." (PMID 34561461, 2021). "CSCs can be regulated by stemness markers (Oct4, Sox2, KLF4, c-Myc, Nanog, and others), signaling pathways (Hh, Wnt, Notch, TGF/BMP, Hippo, and other pro-survival pathways), extracellular factors (hypoxia, Tumor-associated macrophages, ECM, and vascular niches), and other factors." (PMID 33158118, 2020). "Therefore, we hypothesized that miR-7 can play a role as tumor suppressor, through negative regulation of YY1 and KLF4 expression, affecting the cell migration and chemoresistance in NHL." (PMID 33194748, 2020).
tumor (continued). "Notably, tumor #2 exhibited only low LGR5 intestinal stem cell marker expression, but consisted of substantial amounts of enterocytes and secretory progenitor cells as depicted by high HES1 and SPDEF1 as well as moderate KLF4 expression, respectively." (PMID 33628739, 2020). "Inhibition of KLF4 could efficiently block both DNA damage response and HR in BRCA1‐proficient, TNBC tumors that, in turn, generates synthetic lethality for BRCA1‐proficient TNBC tumor cells in combination with blocking PARP function." (PMID 33231937, 2020). "Tumor-associated macrophages (TAM), a critical component of immune cells in the tumor microenvironment are positively correlated with the EpCAM+ population and enhance cancer stem cell-like properties via upregulation of CSC transcription factors Bmi1 and Klf4." (PMID 32466488, 2020). "The expression of KLF4 is reduced in HCC tumors, in comparison with the surrounding non-tumorous tissues, and is negatively correlated with the number of tumors, grades of differentiation, and stages of LNM (lymph node metastasis) and TNM (tumor node metastasis)." (PMID 33266506, 2020). "Our mechanistic studies further revealed that the KLF4 transcriptional function is regulated by several types of posttranslational modifications, including PARP1 in response to DNA damage signal, which determines tumor cell survival in the presence of genotoxic stress." (PMID 33231937, 2020). "Tumor-promoting inflammation is an “enabling characteristic” of cancers, including ESCC, and to date, a number of important murine models for inflammation-mediated ESCC have been developed, including mice with Klf4 overexpression, p120 catenin knockout, or conditional Sox2 knockout." (PMID 30998758, 2019). "Importantly, in CRC patient tumor sections, we observed a negative correlation between KLF4 levels and mesenchymal markers including TWIST, β-catenin, claudin-1, N-cadherin, and vimentin." (PMID 32566755, 2019). "Modifications in DNA methylation pattern and also enrichment of methylated histone signs in the promoter regions of some certain genes like MUTYH, KLF4/6 and WNT1 in different signaling pathways could be a notable key contributors to the upregulation of tumor initiation in CRC." (PMID 31724937, 2019). "It has been suggested that KLF4 together with SNAI1 may promote metastasis by inducing transdifferentiation of tumor cells into endothelial cells by an EMT-dependent mechanism, while other studies have suggested that KLF4 also can promote metastasis by EMT-independent mechanisms." (PMID 29765518, 2018). "Three of the up-regulated cancer stem cell-related genes (KLF4, MYC, and SNAI1) are transcription factors involved in rearrangement of the extracellular matrix and in epithelial to mesenchymal transition (EMT), processes that are important in tumor angiogenesis, invasion, and metastasis." (PMID 29765518, 2018). "Taken together, our findings suggest, for what we believe is the first time, that Klf4 functions as a tumor suppressor in NPC to decrease stemness phenotype, inhibit EMT and prevent tumor progression, suggesting that restoring Klf4 function may provide therapeutic benefits in NPC." (PMID 29212199, 2017). "Similarly, overexpression of KLF4 increased tumor volume and weight in the control cells but not in the CRYAB stable knockdown cells." (PMID 27105535, 2016). "Additionally, the CSCs exhibit expression of the self-renewal genes KLF4, Bmi-1, and Nanog, and have the ability to form sphere-like structures in vitro, and tumor in vivo although not robust." (PMID 27172799, 2016). "Together, the findings in the current study highlight a suppressive role of KLF4 in regulation of EMT-enhanced tumor growth and invasion in HCC cells, and suggest that enhancement of either KLF4 or its downstream miRNAs may substantially improve the current treatment for HCC." (PMID 27102441, 2016).